BRAF (B-Raf proto-oncogene, serine/threonine kinase)
Diseases named in the same sentence as BRAF in open-access papers (continued):
Sharing a sentence is not in itself a finding about the gene and the disease.
pilocytic astrocytoma (continued). "Of those recurrently affected boundaries, two adjacent boundaries between KIAA1549 and BRAF were prone to BA-duplications specifically in samples of pilocytic astrocytoma." (PMID 32024999, 2020). "Pleomorphic xanthoastrocytoma (40-80%), diffuse astrocytoma (30-40%) and ganglioglioma (25-45%) frequently harbor BRAF p.V600E, while in pilocytic astrocytoma (5-10%) or glioneuronal tumors (5%), BRAF p.V600E is less common." (PMID 32164789, 2020). "A phase II study of selumetinib in pediatric patients with pilocytic astrocytoma containing either KIAA1549–BRAF or BRAF V600E showed a sustained response rate of 36% (9/25)." (PMID 31466300, 2019). "In the rare phenomenon of pilocytic astrocytomas with anaplasia, ATRX loss frequently co-occurs with NF1 loss, as well as mutually exclusive alterations in the members of the MAPK pathway (e.g. BRAF)." (PMID 31462295, 2019). "We analysed the location of one such mutation involving exons 8–16 of the KIAA1549 gene fused to the C-terminal domain (exons 9–18) of BRAF (SK:B) reported in human pilocytic astrocytomas." (PMID 30603699, 2018). "In line with this interpretation, recent studies on animal models suggest that a single BRAF kinase activation alone was sufficient to induce pilocytic astrocytomas in mice." (PMID 30279357, 2018). "Gangliogliomas more frequently harbor BRAF p.V600E mutation or other variant BRAF mutations than pilocytic astrocytomas, which most commonly harbor KIAA1549-BRAF fusion." (PMID 29880043, 2018). "DNA methylation array and KIAA1549:BRAF fusion analysis confirmed pilocytic astrocytoma identity of DKFZ-BT66 cells after establishment." (PMID 28002790, 2017). "In pilocytic astrocytomas (WHO grade I), we detected gain of chr7q34, which was associated with the presence of the KIAA1549:BRAF gene fusion, as recently reported by our group via FISH assay on these samples." (PMID 27172220, 2016). "Molecular studies on pilocytic astrocytomas have identified recurrent BRAF gene fusions and other alterations that activate the ERK/MAPK signal transduction pathway." (PMID 26682910, 2015). "Infratentorial posterior fossa pilocytic astrocytomas tend to display a high frequency of the KIAA1549:BRAF fusion." (PMID 24716189, 2014). "KIAA1549:BRAF fusion positive pilocytic astrocytomas also occur less frequently with increasing age." (PMID 24716189, 2014). "Since BRAF duplication has been identified as a mechanism for activation of the MAPK pathway in pilocytic astrocytomas we investigated copy number alterations at the BRAF locus by FISH." (PMID 21479234, 2011). "An individual case with BRAF V600E mutation has been reported for pilocytic astrocytoma and several diffuse astrocytomas (WHO grade II) have also been identified with BRAF V600E mutation." (PMID 21479234, 2011). "These BRAF gene alterations occur in about 60–80% of pilocytic astrocytomas but are infrequent in diffusely infiltrating low-grade astrocytomas." (PMID 19333441, 2009). "Additionally, 58 meningiomas and 6 pilocytic astrocytomas with BRAF fusions were profiled with the same NGS panel." (PMID 41834733, 2026). "Among the 27 infratentorial pilocytic astrocytomas, 25 (92.6%) had BRAF duplication, and within the eight supratentorial midline pilocytic astrocytomas, six also harboured BRAF duplications (75%), and one tumour showed whole chromosome 7 gain in the absence of focal duplication." (PMID 41033792, 2025). "Additionally, the overwhelming majority of OPGs are pilocytic astrocytomas which frequently exhibit BRAF alterations." (PMID 40867225, 2025). "Treatment of pilocytic astrocytoma (PA)-derived KIAA1549:BRAF fusion- (DKFZ-BT66, DKFZ-BT308) or BRAFV600E-driven cells (DKFZ-BT314) in proliferating state (induced by SV40-TAg) or senescent state (no SV40-TAg induction) did not reduce viable cell numbers compared to untreated cells." (PMID 38630384, 2024).
pilocytic astrocytoma (continued). "This precluded training classifiers for molecular alterations (such as BRAF for pilocytic astrocytomas or the medulloblastoma subgroups), which, of course, is an attractive future research direction given the importance of these markers for diagnosis and also, in part, therapeutic stratification." (PMID 38672556, 2024). "Despite, limited data regarding the role of anti-BRAF-targeted therapies in spinal pilocytic astrocytomas, based on available data in their intracranial counterparts, there is a trend to consider anti-BRAF-targeted therapies as the treatment of choice in cases not amenable to resurgery." (PMID 39199553, 2024). "Studies have indicated that BRAF inhibitors could lead to a partial response in patients with BRAF aberrant pilocytic astrocytoma." (PMID 36776329, 2023). "Secondly, KIAA1549-BRAF fusion is the most common BRAF alteration in pilocytic astrocytoma." (PMID 37182181, 2023). "The BRAF fusions were largely attributable to pediatric pilocytic astrocytoma." (PMID 36433963, 2022). "By contrast, in vitro studies on pilocytic astrocytoma cells with BRAF alterations showed a tendency to senescence after an initial period of growth, suggesting that a subgroup of pLGG may exhibit growth deceleration over time." (PMID 36319795, 2022). "In our previous study of BRAF genetic alterations in 45 samples of pediatric LGGs, we found an increased BRAF copy number in 18 of the 47 primary samples tested; 15 of them (83.3%) were pilocytic astrocytomas." (PMID 35574540, 2022). "However, ALK fusions mostly occur in infant hemispheric gliomas (IHG), while pilocytic astrocytomas are mainly characterized by BRAF and RAF1 fusions." (PMID 35169893, 2022). "Additionally, children with BRAF V600E-mutant pilocytic astrocytoma were noted to have remarkably lower ADC means than the wild type and relatively unfavorable clinical outcomes." (PMID 35884462, 2022). "However, for pilocytic astrocytomas, it is reported that BRAF activation promotes pro-cancerogenic senescence via a p16 (INK4a) pathway and causes aberrant activation of the protein kinase pathway." (PMID 34687436, 2022). "This tumor was negative for the somatic variant BRAF p.V600E, one of the most common somatic alterations associated with gangliogliomas and pilocytic astrocytomas." (PMID 34863095, 2021). "Likely, pilocytic astrocytomas display significant molecular heterogeneity with BRAF duplication." (PMID 32856872, 2020). "However, given that the cerebellum is the most common location for pediatric pilocytic astrocytoma, and that BRAF-fusion is the most common driver, this data is highly relevant." (PMID 33206716, 2020). "It has been postulated that the cell of origin in pilocytic astrocytoma may have inherent properties that allow BRAF fusions to drive oncogenesis, but the precise mechanism underlying this finding is not known." (PMID 31466300, 2019). "Some remarkable differences are observed at the level of molecular abnormalities in pediatric and adult pilocytic astrocytomas: BRAF fusions are observed in approximately 30% of patients aged 31 to 40 years, but in only 7% of patients older than 40 years of age." (PMID 30279357, 2018). "Moreover, pilocytic astrocytoma (PA) is characterized by a fusion between the BRAF gene and the locus KIAA1549 (chromosome 7q34)." (PMID 28293477, 2017). "In addition, MLN2480 has recently been shown to suppress pERK and cell proliferation in short term cultures of primary pilocytic astrocytoma cells that were confirmed as positive for the KIAA1549:BRAF fusion gene." (PMID 28002790, 2017). "Importantly, BRAF alterations (V600E mutations and KIAA1549-BRAF fusions) were distributed across multiple diagnostic groups—PLNTY, ganglioglioma, and pilocytic astrocytoma—each of which exhibited a distinct methylation signature." (PMID 27812792, 2017).
pilocytic astrocytoma (continued). "Additionally, FGFR1-TACC1 fusion has been reported in a BRAF wild-type pilocytic astrocytoma of the diencephalon and several studies have reported oncogenic structural FGFR1 variants with duplication of the tyrosine kinase domain." (PMID 28468611, 2017). "Morphologically, the glial component of both tumors are identical, and could explain the finding of KIAA1549:BRAF fusion, that is frequently found in pilocytic astrocytomas." (PMID 26371886, 2015). "In-frame BRAF fusions have been observed in over 80% of sporadic pilocytic astrocytomas." (PMID 25821557, 2015). "The KIAA1549 gene is often fused to the BRAF in cases of pilocytic astrocytoma." (PMID 25423363, 2014). "Another genetic aberration in BRAF in addition to BRAF V600E point mutations that leads to increased kinase activity in low- and high-grade pediatric brain tumors is a fusion protein of KIAA1549:BRAF that is found in the majority of pilocytic astrocytomas." (PMID 23717811, 2013). "In an in vivo flank model of a pediatric pilocytic astrocytoma, subcutaneous xenografts of BT40 (which carries a BRAF V600E mutation) were treated with vehicle, PLX4720, everolimus, or combination of PLX4720 + everolimus, and the outcome measures of tumor size and animal survival were followed." (PMID 23717811, 2013). "Several studies suggest that, unlike the BRAF V600E mutation, the KIAA1549:BRAF fusion is associated with an infratentorial location for pilocytic astrocytomas." (PMID 23717811, 2013). "BRAF, v-RAF murine sarcoma viral oncogene homolog B1, is also an STK and a member of the RAS/RAF/MEK (MAPK kinase)/MAPK pathway that is commonly activated by somatic point mutation V600E in pilocytic astrocytoma." (PMID 24212955, 2011). "The identification of BRAF V600E mutations as a common mutation in PXA offers an ancillary diagnostic tool that can help discriminate PXA from standard GBM and gcGBM as well as pilocytic astrocytoma." (PMID 21479234, 2011). "In a similar fashion, the V600E mutation in BRAF (coded by the BRAF gene) highly correlates with a poorer prognosis and overall survival across a broad spectrum of pediatric LGG, while the KIAA1549-BRAF gene fusion aids in the diagnosis of pilocytic astrocytomas (PA)." (PMID 35363819, 2022). "Although it may resemble pilocytic astrocytoma, no BRAF alteration, fusion, or mutation has been demonstrated." (PMID 34069450, 2021). "And, although rare, it should be noted that BRAF fusions and single nucleotide mutation may occur concurrently, as is the case in an estimated 1–3% of low grade gliomas, 3% of PA and PXA, and 1.6% of pilocytic astrocytomas." (PMID 33042847, 2020). "None of the patients with pilocytic astrocytoma had BRAF V600E mutations." (PMID 30569607, 2019). "However, at the age of 5 (two years before recurrence) he also had a pilocytic astrocytoma, which developed at the cerebral cortex that did not present BRAF V600E mutation." (PMID 30558563, 2018). "In other words, while the presence of IDH mutation is required for the molecular diagnosis of an astrocytoma or oligodendroglioma, in tumours such as ganglioglioma, pleomorphic xanthoastrocytoma or pilocytic astrocytoma the BRAF V600E mutation is not always present." (PMID 29098416, 2018). "Also, typical molecular abnormalities of some entities are not covered by our panel (e.g., fusion genes like RELA fusion genes, relevant for supratentorial ependymoma, BRAF-KIAA fusion gene relevant for pilocytic astrocytoma, FGFR fusion genes, potentially targetable)." (PMID 30470264, 2018). "Hence, enhanced RAS/ERK signaling in the pilocytic astrocytomas by activated BRAF may have triggered a gliogenic switch, and this is reflected in the expression of microRNAs that are usually observed in astroglial cells." (PMID 26682910, 2015). "Preclinical data suggest that BRAF fusions, which are widespread in pilocytic astrocytoma, may not be as responsive to BRAF inhibitors as V600-mutated tumors are." (PMID 24725538, 2014).
pilocytic astrocytoma (continued). "Specifically, genomic profiling based on clinical-grade NGS could identify whether PTEN loss or other GAs activating the mTOR pathway are present alongside the BRAF fusion in a pilocytic astrocytoma of patient, thus suggesting a potential responsiveness to combined sorafenib/mTOR targeted therapy." (PMID 24422672, 2014). "BRAF and/or MEK inhibitors have demonstrated efficacy in pilocytic astrocytomas and glioneuronal tumors, belzutifan in von Hippel–Lindau-related hemangioblastomas, and promising results have been reported with ONC201 in diffuse midline glioma H3-K27M altered." (PMID 39199553, 2024). "Pilocytic astrocytoma patients represent a large proportion of pLGG cases and have a well-described genomic landscape with either a KIAA1549::BRAF fusion or BRAF V600E SNV as the main driver aberrations." (PMID 38371226, 2024). "BRAF fusions with KIAA1549 as a partner gene were observed in 3 patients, all of which were diagnosed with pilocytic astrocytomas." (PMID 39143272, 2024). "Most OPGs are histologically characterized as grade 1 pilocytic astrocytoma (2021 WHO classification), in which KIAA1549-BRAF, BRAF, and NF1 are the commonly altered genes." (PMID 37891793, 2023). "Combined BRAF and MEK inhibition has been proven to significantly improve the outcome of patients with BRAF V600E-mutant pilocytic astrocytoma in a small series of five paediatric cases." (PMID 34360713, 2021). "For example, a tandem duplication event linking BRAF to a nearby gene, KIAA1549, is a recurrent event seen in a majority of pilocytic astrocytomas and represents the predominant neoplastic driver in such cases." (PMID 32493417, 2020). "The low grade glial or glioneuronal tumor cohort comprised samples with BRAF or FGFR1 gene alterations and included 11 dysembryoplastic neuroepithelial tumors, seven pilocytic astrocytomas, and two gangliogliomas." (PMID 33282733, 2020). "It is emerging however, that while these FGFR1-mutant tumors certainly can be described histologically and biologically as low grade, they are distinct from typical pilocytic astrocytoma (WHO grade I), which are predominately driven by BRAF fusions." (PMID 32085805, 2020). "Because of the high frequency of BRAF fusions, a patient-derived KIAA1549:BRAF-driven pediatric pilocytic astrocytoma model has been established for preclinical drug testing and has been used for selected MAPK and MEK inhibitor testing." (PMID 31181803, 2019). "Some of these tumors have BRAF duplications and KIAA1549-BRAF fusions, suggesting that a minority of these tumors share a common molecular background with classical pilocytic astrocytomas." (PMID 31181803, 2019). "BRAF‐V600E immunostaining was detected in 29.5% of cases (41/140 cases; 61.5% GG/GC/AGG (32/52), 33% PXA, 6.6% pilocytic astrocytomas)." (PMID 28293477, 2017). "Following initial comparison with other tumor types, microRNA profiles were then investigated in detail in pilocytic astrocytomas, all of which contained the KIAA1549:BRAF gene fusion." (PMID 26682910, 2015). "The presence of BRAF and RAF1 fusions has been reported to activate mitogen activated kinase-like protein (MAPK) in pilocytic astrocytoma." (PMID 25473895, 2015). "BRAF fusions, occurring in 66% of pilocytic astrocytomas, were demonstrated to arise from the fusion between KIAA1549 and BRAF as a result of a tandem duplication of ~2Mb at 7q34." (PMID 26525348, 2015). "For example, BRAF fusions occur in the majority of pediatric low-grade gliomas (pLGG), with the most common being a KIAA1549::BRAF fusion, present in up to 70% to 80% of pilocytic astrocytomas." (PMID 40111124, 2025). "In the case of BRAF V600E-mutant LEAT, all 16 tumors with Group 1 imaging features were classified as GG and one tumor with Group 3 imaging features (Case 14) was classified as pilocytic astrocytoma." (PMID 39081340, 2024).
pilocytic astrocytoma (continued). "Altogether, alterations in BRAF gene do not only constitute a valuable diagnosis tool and prognostic factor for some cases of LGG, particularly pilocytic astrocytoma, but also represents an interesting candidate for targeted therapy aimed at reducing the constitutively activated MAPK pathway." (PMID 35363819, 2022). "A further limitation of this study is that only a limited set of molecular parameters was assessed, e.g., there was no molecular assessment of the BRAF status in pilocytic astrocytomas." (PMID 33963441, 2021). "As BRAF fusions are identified in a large portion of pilocytic astrocytomas and there is growing evidence supporting the efficacy and tolerability of MEK inhibitors for pediatric LGGs harboring BRAF fusions, our findings have important therapeutic implications." (PMID 33153497, 2020). "Furthermore, all pilocytic astrocytomas in the study’s cohort harbored a MAPK pathway alteration, and Genome MuSiC algorithm suggested that the BRAF, FGFR1, KRAS, and NF1 were the only genes found to be most significantly mutated." (PMID 26525348, 2015). "On a cautionary note, most pilocytic astrocytomas (a distinct diagnosis, but related to anaplastic astrocytoma) carry RAF1 or BRAF rearrangements; thus it is possible that the D538-MG cell line (harboring BCL6/RAF1) was actually derived from a misdiagnosed pilocytic astrocytoma." (PMID 23637631, 2013). "Recent reports have indicated a central role for the mitogen-activated protein kinase (MAPK) pathway in the tumorigenesis of pilocytic astrocytomas and showed that duplication at 7q34 leads to a fusion between KIAA1549 and BRAF resulting in constitutive activation of the BRAF kinase." (PMID 19603027, 2009). "Furthermore, the Pediatric Brain Tumor Consortium (PBTC) data looking at MEKi and OPGs illustrated that even without biopsy, some known pilocytic astrocytomas without a BRAF fusion also had a response." (PMID 40867225, 2025). "For example, the treatment of pilocytic astrocytomas dramatically changed when it was determined that the vast majority result from genetic alterations in the mitogen-activated protein kinase (MAPK) signaling pathway, most often in the BRAF gene, which serves as a therapeutic target." (PMID 32375301, 2020). "It is nevertheless important to note that the presented BRAF multiplexed assay is not designed to detect other rare fusions involving BRAF that have been reported in pilocytic astrocytomas including FAM131:BRAF, RNF130:BRAF, CLCN6:BRAF, MKRN1:BRAF, GNAI1:BRAF, and GTF2I:BRAF." (PMID 33282733, 2020). "Given a limited sample of a pediatric brain tumor featuring piloid glial cells with or without Rosenthal fibers, and eosinophilic granular bodies, the presence of a BRAF fusion may be highly suggestive, but not pathognomonic, of a pilocytic astrocytoma." (PMID 33042847, 2020).